MTOR (mechanistic target of rapamycin kinase)
Diseases named in the same sentence as MTOR in open-access papers (continued):
Sharing a sentence is not in itself a finding about the gene and the disease.
multiple myeloma (138 papers, 2011 to 2025). "The aim of the study was to evaluate the expression and the prognostic value of RGS1 and mTOR and their relation to clinical as well as other diagnostic criteria in multiple myeloma." (PMID 37437037, 2023). "On the other hand, once HMGB1 is decreased, the mTOR pathway is activated to suppress autophagy and trigger apoptosis, increasing the susceptibility of myeloma cells to dexamethasone (Dex)." (PMID 37046991, 2023). "HIF-1a is downstream of the PI3K/AKT/mammalian target of rapamycin (mTOR) pathway and is associated with the progression of myeloma cells through the transcription of several important genes concerning myeloma pathogenesis, such as VEGF and IGF-1." (PMID 33435539, 2021). "The PI3K/mTOR/Akt pathway has been implicated to contribute significantly to the pathogenesis of multiple myeloma through the stimulation of proliferation, resistance and cancer stem cell survival." (PMID 29254208, 2017). "In MM, the PI3K/Akt/mTOR pathway crosstalks with other important signaling pathways implicated in myeloma including the MEK/Erk and Jak/Stat pathways." (PMID 23185517, 2012). "Perifosine can augment the autophagy induced by the mTOR inhibitor sirolimus and cause synergistic cytotoxicity in multiple myeloma cells; this mechanism may present a rationale for designing clinical trials in relapsed/refractory multiple myeloma." (PMID 32410999, 2020). "Our mechanistic studies demonstrate that CKS2 knockdown in multiple myeloma (MM) cells induces PTEN upregulation with concomitant suppression of AKT/mTOR phosphorylation." (PMID 40092696, 2025). "mTOR expression is elevated in various cancers, including gastric, liver, laryngeal carcinoma, pancreatic, prostate, ovarian, and multiple myeloma." (PMID 40754657, 2025). "The role of mTOR-dependent 4EBP1 phosphorylation in c-Myc-driven myeloma was examined in the mouse model Vk*MYC." (PMID 39482742, 2024). "Inhibition of IL-6 mediated signaling by decreasing the expression of its receptor at the transcription level via AMPK, mTOR, and miR-34a is one of the newer mechanisms that suggest metformin as a potential treatment for multiple myeloma." (PMID 38675438, 2024). "Among all ribosome biosynthesis influencers, mammalian target of rapamycin (mTOR) has emerged as therapeutic candidates for multiple myeloma." (PMID 39162964, 2024). "These two key regulators of cell metabolism are downstream effectors of the multiple myeloma survival pathway mTOR." (PMID 36245401, 2023). "In preclinical studies these nanocomplexes were non-toxic and very efficient in different cancer types since they moderated cell viability and hamper mTOR downstream signaling in several xenograft tumor models, including multiple myeloma and breast tumor." (PMID 36871010, 2023). "MET has also been described as a potential therapeutic target for multiple myeloma (MM), where Akt/mTOR is a crucial signaling component through which Met protects multiple myeloma cells from chemotherapy-induced growth inhibition and apoptosis." (PMID 36430388, 2022). "For example, activated FAK/Syk/Akt/mTOR and STAT3 pathways are known to underlie Reelin-driven cancer cell growth and metabolic reprogramming, including glycolysis in myeloma cells." (PMID 35379785, 2022). "GC-induced leucine zipper (GILZ), a GC-target protein to mediate several actions of GCs, has been found to promote apoptosis by inhibition of the Akt/mTOR signaling pathway in myeloma cells." (PMID 35054897, 2022).
multiple myeloma (continued). "For instance, our research group has previously shown that G9a/GLP targeting in myeloma inhibits p-mTOR, followed by a decrease in p-4EBP1 and p-eIF4E, leading to MM apoptosis." (PMID 35105345, 2022). "We further demonstrate that INPP4B inhibits the proliferation and chemosensitivity of myeloma cells via disturbing PI3K/Akt/mTOR signaling and exerts a tumor suppressor effect." (PMID 35070988, 2021). "Preclinical studies of PI3K/AKT/mTOR pathway inhibitors in multiple myeloma have long demonstrated therapeutic potential." (PMID 35127532, 2021). "Interactions with stromal cells produce cytokines like IL-6, VEGF, and IGF-1 which activate the PI3K/AKT/mTOR pathway in multiple myeloma patients, initiating a signaling cascade which promotes resistance to chemotherapy and cancerous progression." (PMID 35127532, 2021). "Further, we observed that when rapamycin and perifosine mutually suppress the PI3K/Akt/mTOR pathway, they induce synergistic multiple myeloma cell cytotoxicity." (PMID 34361836, 2021). "MicroRNA-451 regulates the stemness of side population cells via the PI3K/Akt/mTOR signaling pathway in multiple myeloma." (PMID 34298738, 2021). "For example, recent strategies include AKT/mTOR inhibitors as bortezomib has been shown to increase AKT activation in multiple myeloma cells." (PMID 32198455, 2020). "In fact, it has been previously reported that c-Myc and mTOR converge on a common node in protein synthesis control that confers synthetic lethality in Myc-driven cancers, including multiple myeloma." (PMID 32987735, 2020). "Everolimus shows synergistic anti-myeloma effects with bortezomib through inhibition of the Akt/mTOR pathway in both the MM cell lines and MM-bearing mice model." (PMID 33489922, 2020). "In multiple myeloma, mTOR knock-down inhibited the proliferation of MM cells and rapamycin, which is an inhibitor of mTOR, has been reported to suppress the rate of glycolysis 33,34." (PMID 32626538, 2020). "Combined treatment with GSK2334470 and the mTOR inhibitor PP242 had more potent anti-myeloma activity and led to complete inhibition of mTOR and Akt." (PMID 31817676, 2019). "Blocking the mTOR/PI3K and Rad (Ras associated with diabetes) pathways have also been shown to overcome PI-resistance in lymphoma and hold potential in myeloma." (PMID 29765356, 2018). "Decursin enhanced caspase-9-mediated apoptosis in doxorubicin-treated multiple myeloma cells, via the mTOR and STAT3 pathways and other reports showed that decursin increased caspase-8-mediated apoptosis by increasing TRAIL sensitivity." (PMID 30155480, 2018). "These pathways converge with the mTOR pathway, which is constituently active in myeloma, suggesting a functionally important role for mTOR in myeloma progression." (PMID 29876006, 2018). "Our findings demonstrated that increased thioredoxin plays a critical role in bortezomib resistance in multiple myeloma through mitophagy inactivation and increased mTOR and ERK1/2 phosphorylation." (PMID 29482577, 2018). "Previous studies conducted by our group demonstrated that bufalin activated the AKT/mTOR pathway in myeloma cells, which is considered an essential pathway to disease progression and is related to drug resistance in MM." (PMID 28492559, 2017). "Here, we explore the role of DEPTOR, an mTOR inhibitor, in the terminal differentiation of myeloma cells, and its potential impact on patient survival." (PMID 28420429, 2017). "In this study, the authors reported that by targeting the mir-451-mediated activation of the PI3K/mTOR/Akt pathway with inhibitors Rapamycin and S14161, the myeloma CSC population was directly reduced via apoptosis." (PMID 29254208, 2017). "The regulation of the PI3K/AKT/mTOR pathway is not fully understood with respect to multiple myeloma; however, in most cell types, it is controlled by phosphatases such as PP2A." (PMID 27144172, 2016).
multiple myeloma (continued). "The anti-myeloma effect of the 96 compounds was simultaneously compared to a panel of 68 known PI3K/AKT/mTOR inhibitors." (PMID 27229530, 2016). "It has been recently shown that FK866 induces MTOR de-phosphorylation, thereby inducing autophagic cell death in multiple myeloma cells." (PMID 26542945, 2015). "Given the role of UCH-L1 in modulating mTOR-Akt signaling, and the strong impact this has on myeloma cell survival, these data strongly implicate the Akt survival pathway as being essential in MM cells expressing UCH-L1." (PMID 26513019, 2015). "The mTOR pathway has been suggested to be a potential therapeutic target in myeloma characterized by up-regulated AKT1." (PMID 25769101, 2015). "In this study, we found cytoplasmic p-mTOR expression in almost half of the multiple myeloma samples investigated by immunohistochemistry." (PMID 26097872, 2015). "The mammalian target of rapamycin (mTOR) is extensively involved in multiple myeloma (MM) pathophysiology." (PMID 26329846, 2015). "We evaluated the activation and cellular localization of the mTOR pathway in multiple myeloma (MM) and analyzed the role of pomalidomide in regulating mTOR." (PMID 26097872, 2015). "Here we found that in multiple myeloma cell lines and in primary myeloma cells mTOR is distributed throughout the cell cytoplasm and also nucleus at baseline." (PMID 26097872, 2015). "Enhanced AKT phosphorylation at Ser-473 was also observed, which is in line with the paradoxical activation of AKT by MTORC2 complex following inhibition of MTOR as reported with different MTOR inhibitors in multiple myeloma cells." (PMID 26542945, 2015). "Western blot analysis revealed that mTOR and p-mTOR can be detected in the cytoplasm and in the nucleus at baseline in both myeloma cell lines." (PMID 26097872, 2015). "In the current study, the phosphorylation of mTOR and S6K1 was inhibited by combination of decursin and doxorubicin in three multiple myeloma cells, implying that combination of decursin and doxorubicin induces apoptosis via mTOR/S6K1 pathway." (PMID 23818927, 2013). "It has also been reported that expression of constitutively active mutant 4E-BP1 mimics the effect of rapamycin in enhancing apoptosis in multiple myeloma cells, suggesting that the mTOR inhibitors sensitize cells by inhibiting cap-dependent translation." (PMID 23638184, 2013). "The PI3K/Akt/mTOR signal transduction pathway plays a central role in multiple myeloma (MM) disease progression and development of therapeutic resistance." (PMID 23185517, 2012). "In multiple myeloma, emerging evidence demonstrates that mTOR is an important mediator of cell proliferation and survival." (PMID 24212820, 2011). "mTOR signaling pathway is also deregulated in several hematological malignancies including acute and chronic myeloid leukemia and multiple myeloma." (PMID 24212820, 2011). "Further trials for RGS1 and mTOR targeting in multiple myeloma are recommended." (PMID 37437037, 2023). "Moreover, bortezomib treatment has been shown to promote autophagy in myeloma CAFs by inhibiting p62 and mTOR, inducing LC3, and activating TGF-b." (PMID 37046991, 2023). "In addition, the pathways modulated repeatedly by metformin are the STAT pathway (breast), and the mTOR pathway (breast, prostate, kidney, and myeloma)." (PMID 37370809, 2023). "Additionally, the expression of CD155, a TIGIT high-affinity ligand in multiple myeloma (MM) cells, was decreased by the mTOR signaling pathway." (PMID 37239949, 2023). "RGS1 and mTOR were known to play an important role in the pathogenesis of multiple myeloma." (PMID 37437037, 2023). "Interestingly, CCI-779 (also called temsirolimus), a derivative of rapamycin, is also an mTOR inhibitor and has been studied combined with bortezomib in relapsed or relapsed refractory multiple myeloma (NCT00483262)." (PMID 36845727, 2023).
multiple myeloma (continued). "Moreover, the dual blockade of RSK2 and AKT exerted robust molecular effects on critical gene sets associated with myeloma pathophysiologies, such as those with MYC, mTOR, STK33, ribosomal biogenesis, or cell-extrinsic stimuli of soluble factors, in HMCLs." (PMID 35328342, 2022). "In addition, the major signaling pathways, including Hedgehog, Wingless, Notch and PI3K/Akt/mTOR, are involved in the regulation of self-renewal and differentiation of myeloma CSCs." (PMID 36289430, 2022). "Similarly, mutations or deletions in the tumor suppressor, PTEN, which can disinhibit the pathway can sensitize tumors to mTOR inhibition are uncommon in multiple myeloma." (PMID 35127532, 2021). "Notably, a retrospective analysis found that gene expression profiles of responding myeloma patients were characterized by higher baseline expression of mTOR pathway genes." (PMID 35127532, 2021). "It has been demonstrated that microRNA-451 could regulate the PI3K/Akt/mTOR signaling pathway in multiple myeloma and then contribute to the stemness of side population cells." (PMID 34298738, 2021). "The (mammalian target of rapamycin (mTOR) pathway is known to be activated in multiple myeloma and may play an important role in this process by potentially up-regulating the scavenger receptor (SR-BI), although detailed mechanism information is still elusive." (PMID 33572660, 2021). "However, initial clinical trials, many of which targeted mTOR with rapalogs such as temsirolimus and everolimus, showed muted single agent activity in multiple myeloma patients." (PMID 35127532, 2021). "Multiple growth factors of myeloma cells can also play a role through the PI3K/Akt/mTOR pathway." (PMID 34298738, 2021). "This phenotype could result from the recently reported extensive upregulation of regulatory elements in NF-κB, NOTCH, and MTOR signaling in myeloma cells compared to normal B-cells." (PMID 34845188, 2021). "In many malignant tumors, mTOR is abnormally activated and plays an important role in cell differentiation, proliferation and survival including prostate cancer, ovarian cancer and multiple myeloma 26-28." (PMID 32626538, 2020). "Furthermore, the combination treatment moderately enhanced the cytotoxicity and augmented apoptosis in myeloma cells via suppression of the AKT/mTOR pathway and the downregulation of Bcl-2 and Mcl-1 proteins." (PMID 28492559, 2017). "The PI3K/AKT/mTOR signaling pathway is frequently activated in myeloma." (PMID 28402933, 2017). "To clarify the role of PI3K/AKT/mTOR signaling in the regulation of multiple myeloma cell proliferation and apoptosis by CIP2A, we evaluated the effect of IGF-1 which could activate PI3K on RPMI-8226 and NCI-H929 cells." (PMID 27144172, 2016). "In MM cells the anti-myeloma activity of pomalidomide may be mediated by the regulation of the mTOR pathway." (PMID 26097872, 2015). "Previous studies demonstrates hyper activation of mTOR in myeloma downstream of PI3-K/AKT." (PMID 26097872, 2015). "This is the first report of a mTOR nuclear localization in multiple myeloma." (PMID 26097872, 2015). "Thus, miR-451 targets TSC1 to mediate PI3K/Akt/mTOR signaling, which plays an essential role in myeloma stem cell biology." (PMID 25915427, 2015). "In addition, synergy with targeted therapies such as the mammalian target of rapamycin (mTOR) inhibitor everolimus or the proteasome inhibitor bortezomib, has been described in mantle cell lymphoma and multiple myeloma, respectively." (PMID 23232172, 2012). "Interestingly, our study showed that TOR regulated genome DNA methylation to control plant growth in Arabidopsis, while curcumin induced the promoter hypermethylation of mTOR gene in myeloma cells, suggesting that TOR had a feedback regulation mechanism in the process of regulating DNA methylation." (PMID 32194640, 2020). "Moreover, we show that SEL-DEX inhibits mTOR activity, a key contributor to myeloma progression." (PMID 29876006, 2018).
multiple myeloma (continued). "Also, with the evidence that loss of mTOR resulted in an activation of ERK, the combination of decursin and doxorubicin upregulated the phosphorylation of ERK in the three multiple myeloma cells, indicating that ERK activation is associated with inhibition of mTOR/S6K1 signaling." (PMID 23818927, 2013). "This antibody binds to SLAMF7 on myeloma cells, simultaneously activating NK cells and macrophages through the SLAMF7-EAT2 interaction and stimulating the FYN/Syk-PI3K-Akt/mTOR signaling pathway." (PMID 40646691, 2025). "Previous studies have found that up-regulation of DDIT4 in human myeloma cells inhibits AKT and mTOR signaling and exerts anti-tumor progression effects." (PMID 39593172, 2024). "This study highlighted that C96 curtailed PI3K activation and downregulated the activity of mTOR, p70S6K, and 4E-BP1 in both a time- and concentration-dependent manner, culminating in the apoptosis of multiple myeloma cells." (PMID 38933448, 2024). "Western blot analysis of the mTOR and STAT3 survival pathways showed a significant reduction in p‐mTOR and p‐STAT3 in both LP‐1 and XG‐2 multiple myeloma cells treated with propranolol." (PMID 36245401, 2023). "Previous study found that knocking down CIP2A expression inhibited cell proliferation of human multiple myeloma cells and induced early apoptosis via inactivation of PI3K/AKT/mTOR signaling." (PMID 33948919, 2021). "In the present study, PIWIL1 was found to modulate autophagy-related proteins LC3, p62, and mTOR and the canonical PINK1/PARKIN pathway proteins, indicating that PIWIL1 promoted myeloma growth by modulating autophagy/mitophagy." (PMID 35083142, 2021). "In mature myeloma cells, DEPTOR (DEP domain containing MTOR interacting protein) increases sensitivity to therapeutic agents by inhibiting the activity of mTOR kinases." (PMID 35095893, 2021). "Previous reports have shown that metformin likely arrests myeloma cells at the G0/G1 phase by targeting the AMPK and mTOR pathways in vitro." (PMID 33375360, 2020). "PolyP increases the kinase activity of mammalian target of rapamycin (mTOR) in MCF-7 tumor cells and accumulates at nucleolar transcription sites in myeloma cells." (PMID 31106204, 2019). "Using chemical activator of mTOR and ERK, we demonstrated an important role of mTOR and ERK in the anti-myeloma effects induced by thioredoxin inhibition." (PMID 29482577, 2018). "The FAK/Syk/Akt/mTOR and STAT3 signaling pathways activated by Reelin significantly contribute to the increase in myeloma cell proliferation and glycolysis." (PMID 28345605, 2017). "Our investigation on multiple myeloma cell lines indicates that Reelin-induced activation of integrin β110 and its downstream FAK/Syk results in the phosphorylation of both PI3K/Akt/mTOR and STAT3, providing combinatorial cues for myeloma cell proliferation." (PMID 28345605, 2017). "The PI3K/mTOR/AKT pathway is an integral regulator of survival and drug resistance in multiple myeloma (MM)." (PMID 29254208, 2017). "To analyze the mechanism whereby this combination treatment mediates synergistic anti-myeloma toxicity, we next used immunoblotting to examined the effect of GSK-470, PP242, or combination on AKT/mTOR pathway." (PMID 28402933, 2017). "The present study investigated the role of CIP2A in cell proliferation and apoptosis in the human multiple myeloma cell lines RPMI-8226 and NCI-H929 and its potential regulation of PI3K/AKT/mTOR signaling." (PMID 27144172, 2016). "Kinase and proteasome inhibitor combination treatments are currently being studied in myeloma, including combining aurora-A, Chk1, CDK, Akt, MEK, mTOR, PI3K, and p38 inhibitors with bortezomib." (PMID 27487129, 2016). "Taken together, the results indicate that CIP2A knockdown modulates multiple myeloma cell proliferation and apoptosis via inhibition of PI3K/AKT/mTOR signaling." (PMID 27144172, 2016).